FGF21 (fibroblast growth factor 21)
Diseases named in the same sentence as FGF21 in open-access papers (continued):
Sharing a sentence is not in itself a finding about the gene and the disease.
cholestasis (2 papers, 2024 to 2025). Impairment of the bile flow caused by obstruction within the liver, or outside the liver in the bile duct system. "Second, given that cholestasis is often caused by BA transportation and resorption dysbiosis, the BA pool and related gene expressions in treatment with FGF21 or NaB need to be studied further." (PMID 39040469, 2024). "Importantly, our results indicate that NaB has detrimental effects on cholestasis mice with FGF21 deficiency." (PMID 39040469, 2024). "These comprehensive findings suggest that NaB administration can be a novel nutritional therapy for treating cholestasis by boosting FGF21 signaling and regulating the gut microbiota." (PMID 39040469, 2024). "To confirm the potential therapeutic effects of FGF21 on cholestasis, we administered FGF21 to the WT-BDL mice." (PMID 39040469, 2024). "NaB administration can thus be a novel nutritional therapy for treating cholestasis via boosting FGF21 signaling and regulating the gut microbiota." (PMID 39040469, 2024). "Our results thus indicate that NaB administration could be an alternative approach to boosting FGF21 signaling and regulating gut microbiota in the treatment of cholestasis." (PMID 39040469, 2024). "FGF21 plays a key role in alleviating cholestasis-induced liver damage and fibrosis." (PMID 39040469, 2024). "Together, our results indicate that FGF21 could act as a therapeutic target and that NaB could be an alternative approach for boosting FGF21 signaling in the prevention and treatment of cholestasis." (PMID 39040469, 2024). "We also show that the beneficial effects of NaB on cholestasis are dependent on FGF21." (PMID 39040469, 2024). "NaB administration could highly induce hepatic FGF21 to protect against BDL-induced cholestasis, and this beneficial effect of NaB was FGF21-dependent." (PMID 39040469, 2024). "Additionally, we analyzed the single-cell sequencing data of primary sclerosing cholangitis (PSC) patients and found significant changes in FGF21 expression, indicating the potential of FGF21 as a therapeutic target in the treatment of cholestasis." (PMID 39040469, 2024). "NaB has beneficial effects on cholestasis in an FGF21-dependent manner." (PMID 39040469, 2024). "Previous works, including ours, indicate that the beneficial effects of NaB on boosting FGF21 signal could be a potential strategy in the treatment of cholestasis-induced liver damage and fibrosis." (PMID 39040469, 2024). "However, it remains unknown whether NaB could alleviate cholestasis-induced liver injury and fibrosis; further, it should be identified whether FGF21 is involved in the beneficial effects of NaB." (PMID 39040469, 2024). "The potent induction of FGF21 by PPARA and the effect of its agonist on cholestasis are already known, and the linkage between PPARD and PPARA in the regulation of cholestasis is a subject for future research." (PMID 39899669, 2025).
chronic heart failure (2 papers, 2017 to 2022). "The role of FGF21 and BNP in the prognosis of chronic heart failure is similar." (PMID 35369322, 2022).
chronic liver failure (2 papers, 2020 to 2023). Liver failure that develops slowly and gradually for some time, possibly for years, often as the result of cirrhosis, or malnutrition. "In a study to evaluate FGF21 as a marker of mitochondrial dysfunction in the context of acute-on-chronic liver failure, FGF21 levels and IL6 were found increased in peripheral blood samples of the patients." (PMID 32397676, 2020).
chronic progressive external ophthalmoplegia (2 papers, 2017 to 2020). "We suggest that a high serum concentration of FGF-21 would be clinically useful in MD, especially in adult patients with chronic progressive external ophthalmoplegia, and may enable bypassing muscle biopsy and directly opting for genetic analysis." (PMID 28825656, 2017).
Crohn disease (2 papers, 2022 to 2024). A gastrointestinal disorder characterized by chronic inflammation involving all layers of the intestinal wall, noncaseating granulomas affecting the intestinal wall and regional lymph nodes, and transmural fibrosis. "However, FGF19 and FGF21 pathways (involved in Crohn’s disease and lipid metabolism, respectively) are mediated by β-Klotho, as opposed to α-Klotho." (PMID 34542150, 2022).
Cushing syndrome (2 papers, 2011 to 2021). Cushing's syndrome (CS) encompasses a group of hormonal disorders caused by prolonged and high exposure levels to glucocorticoids that can be of either endogenous (adrenal cortex production) or exogenous (iatrogenic) origin. "Serum FGF21 levels are also increased in patients with Cushing's syndrome." (PMID 21331285, 2011).
endotoxemia (2 papers, 2013 to 2022). "Thus, FGF21-deficient mice are more easily to die of endotoxemia, and initiated administration of FGF21 after bacterial inflammation can get a better survival." (PMID 36440004, 2022). "Circulating FGF21 is liver derived, and it maintains thermoregulation and preserves cardiovascular function during bacterial inflammation, and finally decreased the mortality in endotoxemia." (PMID 36440004, 2022). "Indeed, treatment with exogenous FGF21 reduced the rate of death and the rapidity of death after endotoxemia, suggesting that the increase in plasma FGF21 during an inflammatory state may be a protective response." (PMID 23999826, 2013).
female infertility (2 papers, 2012 to 2015). Diminished or absent ability of a female to achieve conception. "The FGF21-Tg mice share other phenotypic similarities with long-lived dwarf mice including small size, reduced circulating insulin and IGF-1 concentrations, increased circulating adiponectin levels and female infertility." (PMID 23066506, 2012).
Friedreich ataxia (2 papers, 2013 to 2022). An inherited condition that affects the nervous system and causes movement problems. "Serum FGF-21 levels were determined using ELISA in 47 mitochondrial patients, including 32 with primary MIDs, 15 patients with Friedreich ataxia as a secondary MID and 30 control subjects." (PMID 24078096, 2013).
Graves disease (2 papers, 2022 to 2024). Graves' disease is an autoimmune disorder that leads to overactivity of the thyroid gland (hyperthyroidism).It is caused by an abnormal immune system response that causes the thyroid gland to produce too much thyroid hormones. "The vast majority of the subjects had Graves’ disease, and after treatment, a decline in FGF21 was detected as well." (PMID 39452947, 2024). "On the contrary, Xiao and colleagues demonstrated elevated FGF21 serum levels in 119 Graves’ disease hyperthyroid patients compared to healthy controls." (PMID 35909532, 2022).
Headache (2 papers, 2021 to 2026). Cephalgia, or pain sensed in various parts of the head, not confined to the area of distribution of any nerve. "With increasing average headache intensity, serum concentrations of both FGF-21 and GDF-15 were slightly higher." (PMID 34572118, 2021). "A cross-sectional study in two headache centers was conducted analyzing GDF-15 and FGF-21 serum concentration in 230 patients with episodic and chronic migraine compared to a control group." (PMID 34572118, 2021). "In SRC, it was reported that headaches showed a significant negative correlation with the expression of serum fibroblast growth factor 21 (FGF21), within 3 months of injury." (PMID 41574089, 2026).
hyperhomocysteinemia (2 papers, 2015 to 2016). A serious metabolic condition caused by mutations in the MTHFR gene, medications, or nutritional deficiency. "An MR diet induces the secretion of the cardioprotective hormones, adiponectin and FGF21, indicating that the adaptive responses of increased serum adiponectin and FGF21 levels protect against hyperhomocysteinemia." (PMID 27803896, 2016). "Our findings demonstrate that MR diet does not alter cardiac function in mice despite the presence of hyperhomocysteinemia because of the adaptive responses of increased adiponectin and FGF21 levels." (PMID 25744495, 2015). "Here, we report that MR induces hyperhomocysteinemia without affecting cardiac function, which is possibly a result of compensatory mechanisms elicited by the hepatic and adipose tissue secretions of the cardioprotective hormones FGF21 and adiponectin, respectively." (PMID 25744495, 2015).
hypogonadotropic hypogonadism (2 papers, 2017 to 2021). Abnormal ovarian or testicular function due to insufficient hormonal stimulation from the hypothalamic-pituitary axis. "Mice overexpressing FGF-21 exhibit hypogonadotropic hypogonadism." (PMID 33764994, 2021).
insulinoma (2 papers, 2017 to 2019). "Multiple regression analysis showed that fasting insulin (β = 0.80, P = 0.003) was an independent predictor of serum FGF21 levels in subjects with insulinoma." (PMID 28225059, 2017). "The present study provides the first evidence that shows that the FGF21 concentrations were significantly increased in patients with insulinoma and decreased after removing the tumor." (PMID 28225059, 2017). "In conclusion, a key strength of this study is the observation of dynamic changes of FGF21 in patients with insulinoma." (PMID 28225059, 2017). "Furthermore, FGF21 was positively correlated with insulin (r = 0.80, P = 0.003) and proinsulin (r = 0.72, P = 0.012) in subjects with insulinoma." (PMID 28225059, 2017). "Interestingly, we found that the serum FGF21 levels increased significantly in patients with insulinoma at baseline compared with the control group (381.36 ± 107.12 vs. 62.59 ± 10.48 pg/mL; P = 0.001)." (PMID 28225059, 2017). "This implies that FGF21 contributes to the metabolic adaptations of the body to insulinoma." (PMID 28225059, 2017). "However, in the present study, we found that increased FGF21 concentrations in patients with insulinoma and decreased significantly after tumorectomy." (PMID 28225059, 2017). "In addition, the changes in the plasma FGF21 levels were positively correlated with the changes in insulin (r = 0.61, p = 0.048), proinsulin (r = 0.84, p = 0.001), C-peptide (r = 0.48, p = 0.137) and plasma glucose (r = 0.20, p = 0.558) in patients with insulinoma." (PMID 28225059, 2017). "Although FGF21 might be increased by metabolic stress in patients of insulinoma and decreased after the surgery, the correlation of FGF21 with fasting plasma glucose had not been found in our study." (PMID 28225059, 2017).
intrauterine growth restriction (2 papers, 2015 to 2025). "GLUT3 in intrauterine growth restriction was colocalized with the hypoxic transcription factor HIF-1α whereas FGF21 has been reported to induce GLUT1 expression in adipocytes." (PMID 25890271, 2015). "Other studies suggest FGF21 signaling exerts a negative effect on myogenesis and promotes atrophy in different physiological and disease contexts including fasting, aging, intrauterine growth restriction, and short-term pharmacological administration." (PMID 40788112, 2025).
iron-overload (2 papers, 2021 to 2023). "With the occurrence of brain FGF21 resistance, the reduction of the expression of synaptic proteins and development of Alzheimer’s like pathology in iron-overloaded thalassemia mice model." (PMID 33850218, 2021). "Taken together, these findings suggest that the association of FGF21 level and MCI condition in thalassemia patients was independently related to the severity of iron-overload status (high serum ferritin and maximum level of serum ferritin in the past 5 years)." (PMID 33850218, 2021). "Nonetheless, any association of FGF21 in relation to the MCI of thalassemia patients as well as the underlying mechanism associated with FGF21 in cases of iron-overload have never been investigated." (PMID 33850218, 2021).
lactic acidosis (2 papers, 2017 to 2024). Metabolic acidosis characterized by the accumulation of lactate in the body. "Anecdotally, in two patients undergoing intensive care, the highest values were associated with respiratory deterioration (but without lactic acidosis), consistent with the high serum FGF-21 concentrations in patients undergoing intensive care." (PMID 28825656, 2017).
liver neoplasm (2 papers, 2018). Tumors or cancers of the LIVER. "Animals treated with AAV8‐hAAT‐FGF21 vectors were protected from HFD‐induced development of liver neoplasms: 0% (0/8) of animals treated with the 5 × 1010 vg of FGF21‐encoding vectors showed tumors, and the incidence was 40% (4/10) in the cohort treated with the lowest dose (1 × 1010 vg)." (PMID 29987000, 2018). "Regarding tumor formation, although the number of animals used in our studies was low, the striking difference in the incidence of liver neoplasms between animals injected with null vectors or therapeutic vectors actually argues in favor of a protective role of FGF21 against malignancies." (PMID 29987000, 2018). "Importantly, these levels of circulating FGF21 did not produce bone toxicity in mice and prevented the development of liver tumors associated with long‐term HFD feeding." (PMID 29987000, 2018).
lung disease (2 papers, 2022). "The diversiform effects that FGF21 plays in pulmonary disease are still fogged." (PMID 35677107, 2022). "In recent years, the effect of FGF21 in lung disease has also received increasing attention." (PMID 35677107, 2022). "Based on the recent evidence, FGF21 might be a new effective method for the treatment of ALI, and further studies are required to investigate the underlying mechanisms and explore the potential clinical use of FGF21 for lung disease in the future." (PMID 36440004, 2022).
melanoma (2 papers, 2020 to 2022). A malignant, usually aggressive tumor composed of atypical, neoplastic melanocytes. "This controversy reflected the pleiotropic actions of FGF21 in melanoma and the tumor microenvironment." (PMID 36263162, 2022). "This is of interest in the context of adipose biology, as WAT-derived sEVs have widespread effects, from regulation of hepatic FGF21 expression and glucose handling by the liver to promotion of fatty acid oxidation within melanoma cells, contributing to aggressive tumor cell migration and invasion." (PMID 32919095, 2020).
Mitral regurgitation (2 papers, 2021 to 2023). An abnormality of the mitral valve characterized by insufficiency or incompetence of the mitral valve resulting in retrograde leaking of blood through the mitral valve upon ventricular contraction. "Univariate Cox analysis showed that a high FGF21 level was a predictor for MACEs in STEMI patients, in addition to age, creatinine, troponin I, NT-proBNP, pulmonary pressure, mitral regurgitation, LAD, LVESD, LVESV and LVEF." (PMID 34703671, 2021).
morbid obesity (2 papers, 2020 to 2022). An excess of body weight, normally defined as an individual with a body mass index greater than 35 or a body weight greater than one hundred percent of ideal body weight. "A trial in individuals with T2DM and morbid obesity did report that weight loss of ~6.5 kg upon a 3-week very-low-calorie diet was accompanied by a less pronounced decline in postprandial in FGF21 levels up to 3 h after a mixed meal." (PMID 36501091, 2022). "The metabolic effect of FGF21 might be attenuated by morbid obesity at baseline; nevertheless, after the excess weight was reduced, the association between FGF21 and insulin secretion was restored." (PMID 32210348, 2020). "The strength of our study is that we compared the circulating BDNF/FGF21, clinical characteristics, and biochemical parameters in patients with morbid obesity before and 6 months after LSG." (PMID 32210348, 2020). "Generally, the studies that report a change in plasma fasting FGF21 were performed in individuals with more severely impaired metabolic health (e.g., T2DM, NAFLD, morbid obesity), who typically have elevated FGF21 levels and thus more room for improvement compared to individuals in this study." (PMID 36501091, 2022). "The circulating level of FGF21 was higher in the diabetic patients with morbid obesity than the non-diabetic subjects, while the level of BDNF was similar between the two groups." (PMID 32210348, 2020). "In addition, the associations between FGF21 and several insulin-related profiles, including C-peptide, insulin, and HOMA-IR, after LSG were not noted in the patients with morbid obesity before surgery." (PMID 32210348, 2020).
muscle disorders (2 papers, 2023). "This review focuses on assessing the significance of FGF21 in regulating muscle metabolic homeostasis and explores the advantages of FGF21 in the prevention and treatment of muscle disorders." (PMID 38069273, 2023). "FGF-21 is promising for the replacement of muscle biopsies in diagnosing MD related to muscle disorders." (PMID 37144479, 2023).
myasthenia gravis (2 papers, 2022 to 2025). Myasthenia gravis (MG) is a rare, clinically heterogeneous, autoimmune disorder of the neuromuscular junction characterized by fatigable weakness of voluntary muscles. "FGF21 secretion is increased in myasthenia gravis and mitochondrial stress states, and FGF21 regulates skeletal muscle glucose uptake and protein synthesis." (PMID 40801027, 2025).
neuroblastoma (2 papers, 2021 to 2025). Neuroblastoma (NB) is the most common solid, extracranial childhood tumor. "FGF21 suppresses Aβ1–42-induced cell inflammation and apoptotic death in SH-SY5Y neuroblastoma cells." (PMID 39876880, 2025).
organic acidemia (2 papers, 2018 to 2025). "This study provides new insights into the potential role of FGF-21 as a biomarker for predicting long-term complications in organic acidemias." (PMID 30159853, 2018). "This study demonstrates that FGF-21 can be a biomarker for long-term complications, attributed to mitochondrial dysfunction, in classic organic acidemia patients." (PMID 30159853, 2018). "This study demonstrates the potential role of FGF-21 as a biomarker for long-term complications in classical organic acidemias, attributed to mitochondrial dysfunction." (PMID 30159853, 2018). "We studied the potential of serum FGF-21 measured in the stable metabolic period as a biomarker for long-term complications, attributed to mitochondrial failure, in patients with organic acidemias." (PMID 30159853, 2018). "From this perspective, markers of mitochondrial dysfunction, such as fibroblast growth factor 21 (FGF-21) and growth differentiation factor 15 (GDF-15), could be promising prognostic indicators of organic acidemia complications associated with mitochondrial dysfunction." (PMID 41399536, 2025).